SLC1A2 (solute carrier family 1 member 2)
Diseases named in the same sentence as SLC1A2 in open-access papers (continued):
Sharing a sentence is not in itself a finding about the gene and the disease.
autism (20 papers, 2009 to 2026). Persistent deficits in social interaction and communication and interaction as well as a markedly restricted repertoire of activity and interest as well as repetitive patterns of behavior. "In terms of genetics, Glu transporter genes are functional candidates for autism, and single-nucleotide polymorphisms in the SLC1A1 and SLC1A2 Glu transporter genes are associated with autism (Jacob, Landeros-Weisenberger, & Leckman, 2009)." (PMID 39564744, 2024). "Altogether, these findings warrant further investigations in this era, particularly pertinent to the epigenetic silencing of SLC1A2, as its deletion and knockout are linked to autism phenotype in humans and mice." (PMID 38994948, 2024). "Consistent with our findings, there are some reports that reduced expression of SLC1A2 contributes to the pathogenesis of autism and other major mental diseases and that the deletion of 11p14-p12, which includes SLC1A2, is linked to autism phenotype." (PMID 38994948, 2024). "Large-scale genetic analyses for disease-associated genes have indicated a link between the SLC1A2 (GLT1) gene and autism." (PMID 23506860, 2013). "In postmortem brain samples, we found DNA hypomethylation of TGFB2 and IFI16 promoter regions, but DNA hypermethylation of HAP1 and SLC1A2 promoters in autism." (PMID 38994948, 2024). "Glutamate transporter genes are functional candidates for autism, and single-nucleotide polymorphisms (SNPs) in SLC1A1 and SLC1A2 glutamate transporter genes are associated with autism." (PMID 35296811, 2022). "Candidate genes such as BDNF, ELP4, PRRG4, and SLC1A2 have been identified in relation to autism, cognitive/developmental delays, and behavioral problems." (PMID 34970513, 2021). "SLC1A3, which is similar to SLC1A2, involved in rapid glutamate removal from the synaptic cleft and had >4-fold higher expression in astrocytes vs. neurons, was also decreased by 90% only in the astrocytes of patients with autism (p = 0.002)." (PMID 38994948, 2024). "However, we found reduced expression of SLC1A2 in iPSC-derived astrocytes in autism, as well as DNA hypermethylation of its promoter in the postmortem brains of patients with autism." (PMID 38994948, 2024). "SLC1A2, a glucose/glutamate transporter, was among other genes whose expression was greatly reduced in the astrocytes (90%, p = 0.045) but insignificantly in the neurons (50%, p = 0.2) of patients with autism vs. controls." (PMID 38994948, 2024). "The SLC1A2 promoter region was also hypermethylated (~300%, Mean ± SEM 1 ± 0.4 and 3.3 ± 0.7 in controls and autism, respectively, p = 0.02) in the brains of patients with autism, though its overall promoter DNA methylation was trivial (~5% in controls and 15% in autism)." (PMID 38994948, 2024). "There was no significant alteration in SLC1A2 expression in the NSCs of patients with autism vs. controls, suggesting that its expression alteration happens after astrocyte/neuronal differentiation." (PMID 38994948, 2024). "From the total set of genes constituting the NBC, 233 candidates occur in at least 5 sibling conditions, 74 are present in 7 or more siblings, 29 in 8 or more, 13 in 9 autism siblings, 3 in 10 autism sibling disorders (MAGI2, NR3C1, SLC1A2) and one (SLC1A2) present in 12 siblings." (PMID 28427329, 2017). "In addition to proinflammatory genes, there are also reports of reduced expression of several key neuronal genes such as RELN, SLC1A2, GAD1, TSC1 and HAP1 in autism or autism spectrum disorders, which have not been causally linked to neuro-inflammation in autism." (PMID 38994948, 2024).
ischemic stroke (17 papers, 2013 to 2025). A stroke disorder caused by obstruction of blood flow to the brain, due to thrombotic (local blood clot formation) or embolic (due to a blood clot or other material traveling from another site) event. "Our results showed that Slc1a2 (the name of the gene that encodes GLT-1), displayed a downregulated trend after the CIR-induced ischemic stroke, thus pinpointing the induction of excitotoxicity in the brain." (PMID 26492191, 2015).
cognitive decline (16 papers, 2016 to 2025). "In the meantime, EA improved cognitive decline, possibly targeted at the transmembrane protein 126A (TMEM126A) and the excitatory amino acid transporters (SLC1A2/EAAT2) in rats with neuropathic pain." (PMID 38379403, 2025).
bipolar disorder (12 papers, 2015 to 2026). A disorder of the brain that causes unusual shifts in mood, energy, activity levels and the ability to carry out day-to-day tasks. "A particular gene-by-environment interaction of early experienced stress and the functional polymorphism rs4354668 in SLC1A2 has been shown in the hippocampal gray matter in subjects with bipolar disorder." (PMID 36233781, 2022). "Additionally, SLC1A2 polymorphism was shown to significantly influence other mental health disorders related to the total episode recurrence rate in bipolar disorders, with G homozygotes reporting the highest number (p = 0.004)." (PMID 36836504, 2023). "The SLC1A2 rs4354668 polymorphism was reported to influence the total episode recurrence rate and the efficacy of lithium treatment response in a sample of Italian patients with bipolar disorder." (PMID 36233781, 2022). "DNA hypermethylation of the SLC1A2 promoter region was also shown in the blood cells of patients with bipolar disorder." (PMID 38994948, 2024). "However, one study reported that patients who showed concurrent bipolar disorders and binge-eating had hypomethylation of the SLC1A2 gene (involved in removing glutamate from the synaptic cleft) relative to patients with bipolar disorder who displayed no binge eating." (PMID 32375223, 2020).
essential tremor (7 papers, 2013 to 2023). A relatively common disorder characterized by a fairly specific pattern of tremors which are most prominent in the upper extremities and neck, inducing titubations of the head. "In the genetic aspect, one variant (rs3794087) of the SLC1A2 gene encoding EAAT2 seems to be related with essential tremor, though some other studies doubted this association." (PMID 32982923, 2020). "An essential tremor SNP (rs3794087 of SLC1A2) is associated with a decreased risk of PD in the Eastern Han Chinese population, while rs9652490 (LINGO1) and rs17590046 (PPARGC1A) do not show an association." (PMID 31755235, 2020). "Genetic polymorphisms in Solute carrier family 1 (glial high affinity glutamate transporter), member 2 (SLC1A2) have been linked with essential tremor." (PMID 25391854, 2014). "MKLN1 has been previously associated with childhood asthma, SORBS1 with suicide risk and childhood obesity in Hispanics, SLC1A2 with fatty acid levels, essential tremor, and other traits, EPB41L4B with wound healing, PTPN3 with cancer, and FGF3 with breast cancer and deafness." (PMID 26569114, 2015).
alcohol dependence (6 papers, 2014 to 2024). Physical and psychological dependence on alcohol. "However, alcohol dependence was reported to be associated with this SLC1A2 gene polymorphism in the German population." (PMID 36836504, 2023). "Moreover, a significant association between an SLC1A2 SNP, the synonymous G603 A (rs752949) in exon 5, has also suggested the susceptibility of this gene to risk-taking behaviour in alcohol dependence." (PMID 36836504, 2023). "Furthermore, SLC1A2 gene variants are reported to be linked with alcohol dependence which indicates their potential association with drug dependence." (PMID 36836504, 2023).
Dyskinesia (6 papers, 2020 to 2026). A movement disorder which consists of effects including diminished voluntary movements and the presence of involuntary movements. "It has been established that miR-543-3p directly regulated GLT-1 mRNA (SLC1A2 gene), and the inhibition of miR-543-3p upregulated GLT-1 protein expression and function, alleviating dyskinesia in PD models." (PMID 36710937, 2022).
breast carcinoma (5 papers, 2013 to 2025). "We have previously reported that ET-resistant breast cancers exhibit enhanced expression of the glutamate and aspartate transporter SLC1A2, which supports the metabolic demands sustaining tumor aggressiveness." (PMID 40410608, 2025). "These points collectively warrant further investigation into the potential regulatory mechanisms involving CD44 and SLC1A2 in ET-resistant breast cancers." (PMID 40410608, 2025). "The apparent independence of these features in ET-resistant breast cancers prompted us to investigate potential interactions between CD44 and SLC1A2, hypothesizing that they might share regulatory mechanisms." (PMID 40410608, 2025).
Epileptic encephalopathy (5 papers, 2020 to 2025). A condition in which epileptiform abnormalities are believed to contribute to the progressive disturbance in cerebral function. "Furthermore, severe forms of epileptic encephalopathy (EE), characterized by early onset and multiple seizure types combined with developmental slowing or even regression, are linked to mutations in the gene coding for EAAT2 (SLC1A2)." (PMID 40308755, 2025). "Two homologous mutations, which predict substitutions of prolines in the center of the fifth transmembrane helix by arginine (P289R EAAT2, P290R EAAT1), have been identified in patients with epileptic encephalopathy (SLC1A2) or with episodic ataxia type 6 (SLC1A3)." (PMID 37538371, 2023).
gastric cancer (5 papers, 2013 to 2022). A primary or metastatic malignant neoplasm involving the stomach. "CD44-SLC1A2/EAAT2 gene fusions are detected in 1–2 % of gastric cancers involving the glutamate transporter SLC1A2, and cause intracellular accumulation of glutamate, a growth-promoting amino acid associated with oncogenic functions." (PMID 26684754, 2015). "Analogous to TMPRSS2/ERG in prostate cancer, the SLC1A2 fusion in gastric cancer is thought to be driven by strong expression of its 5′ partner, CD44." (PMID 23637631, 2013). "All of these breakpoints occur within intron 1 of SLC1A2, the same position found to be disrupted in several gastric cancers." (PMID 23637631, 2013). "Our DBA results suggested that SLC1A2 rearrangements occur in cancer types other than gastric carcinomas." (PMID 23637631, 2013). "In addition to detecting a known SLC1A2 rearrangement in the gastric cancer cell line SNU-16, DBA identified breakpoints disrupting SLC1A2 in the colon cancer cell line SNU-C1 and in a pancreatic cancer xenograft." (PMID 23637631, 2013). "We show that in addition to CD44/SLC1A2 in gastric cancer, SLC1A2 is involved in a novel but analogous gene fusion, APIP/SLC1A2, in colon cancer." (PMID 23637631, 2013).
glaucoma (5 papers, 2011 to 2020). Increased pressure in the eyeball due to obstruction of the outflow of aqueous humor. "Therefore, genetic association studies of the SLC1A2 gene, which encodes GLT-1, might be needed to clarify which transporter is the primary glutamate transporter related to glaucoma pathogenesis." (PMID 21528001, 2011).
autism spectrum disorder (4 papers, 2018 to 2026). A spectrum of developmental disorders that includes autism, and Asperger syndrome. "For example, Slc1a2, Prdm16, Kank1 and Ddah1 were target genes of Dbx2, the high expression of Slc1a2 was found to reduce the risk for PD in a Chinese cohort and the other genes are associated with cognitive function, autism spectrum disorder and depression-like behavior, respectively." (PMID 36142685, 2022).
psychosis (4 papers, 2011 to 2023). "Our study suggests that the SLC1A2 rs4755404 gene polymorphism confers some susceptibility to METH-induced psychosis, especially for those who carry the GG homozygous genotype." (PMID 36836504, 2023). "The present study investigated the genetic association between SLC1A2 rs4755404 polymorphism and METH dependence and METH-induced symptoms, such as psychosis and mania." (PMID 36836504, 2023). "Our study investigated the association of rs4755404 single nucleotide polymorphism (SNP) of the SLC1A2 gene with methamphetamine (METH) dependence and METH-induced psychosis and mania in a Malaysian population." (PMID 36836504, 2023). "Other SLC1A2 polymorphisms should be investigated as they may contribute to the risk of developing METH dependence and METH-induced psychosis and manic episodes." (PMID 36836504, 2023).
status epilepticus (4 papers, 2017 to 2022). Status epilepticus is defined as a continuous seizure lasting more than 30 min, or two or more seizures without full recovery of consciousness between any of them. "Real-time PCR analysis showed the expected higher levels of Arc, FosB, Inhba, Npas4, Pchd8 and Tll1 bound to Upf1 after status epilepticus whereas levels of Slc1a2 were not different between groups." (PMID 28128343, 2017).
colorectal cancer (3 papers, 2013 to 2025). A primary or metastatic malignant neoplasm that affects the colon or rectum. "Furthermore, analysis of a publicly-available colorectal cancer gene-expression dataset demonstrated SLC1A2 to be expressed at higher levels in SNU-C1 compared to all other cell lines interrogated." (PMID 23637631, 2013). "In colorectal cancer, METTL3 has been shown to have an oncogenic role by stabilizing HK2 and SLC1A2 mRNA via the IGF2BPs axis, regulating glycolytic metabolism and cell proliferation." (PMID 40746529, 2025).
tauopathy (3 papers, 2019 to 2024). Neurodegenerative disorders involving deposition of abnormal tau protein isoforms (tau proteins) in neurons and glial cells in the brain. "Slc1a2 (Eaat2) is a glutamate transporter with a primary role in presynaptic and astrocytic glutamate reuptake and protection from excitotoxicity associated with TBI, tauopathy, and AD." (PMID 38542311, 2024).
Alexander disease (2 papers, 2013 to 2018). Alexander disease (AxD) is a rare neurodegenerative disorder of the astrocytes comprised of two clinical forms: AxD Type I and Type II manifesting with various degrees of macrocephaly, spasticity, ataxia and seizures and leading to psychomotor regression and death. "GFAP, encoding glial fibrillary acidic protein, linked to expression of the glutamate transporter Glt1 (SLC1A2) in Alexander disease, was also over-expressed in affected animals (FC 2.60)." (PMID 23782433, 2013).
dependence (2 papers, 2015 to 2023). "Lastly, the sample size in our study was small and included less evidence to confirm our finding that METH-induced symptoms and dependence were influenced by SLC1A2 rs4755404 polymorphism." (PMID 36836504, 2023). "However, the association between SLC1A2 gene polymorphism and drug dependence with drug abuse remains unknown." (PMID 36836504, 2023). "Furthermore, the effect of the SLC1A2 rs4755404 polymorphism on the onset age of METH-induced symptoms and dependence was also analyzed." (PMID 36836504, 2023). "Therefore, our case-control study aims to establish the association of SLC1A2 rs4755404 genetic polymorphism with METH-induced symptoms and dependence, which is a move forward regarding personalizing medicine in the Malaysian population." (PMID 36836504, 2023). "Together, these findings support a role for Slc1a2 in alcohol intake and dependence." (PMID 25803291, 2015).
hepatocellular carcinoma (2 papers, 2016). A malignant tumor that arises from hepatocytes. "In hepatocellular carcinoma (HCC), activating mutations in β-catenin increase the expression of the glutamate transporter (EAAT2, also known as SLC1A2), as well as of glutamine synthetase." (PMID 27635066, 2016).
WAGR syndrome (2 papers, 2012 to 2021). WAGR syndrome (Wilms tumor - aniridia - genitourinary anomalies - intellectual disability mental retardation) is a rare genetic disorder characterized by an unusual complex of congenital developmental abnormalities with intellectual disability, and an increased risk of developing Wilms tumor. "Further research is needed to explore potential mechanisms leading to seizures in patients with WAGR syndrome, as a variety involving the common WAGR genes and SLC1A2 and ELP4 genes have been suggested." (PMID 34970513, 2021).
colon cancer (1 paper, 2013). "SLC1A2 fusions therefore also represent potential therapeutic targets in gastric and now colon cancer." (PMID 23637631, 2013). "By paired-end RNA sequencing (RNA-seq) of SNU-C1 cells, we uncovered a novel colon cancer gene fusion, APIP/SLC1A2." (PMID 23637631, 2013).
ductal carcinomas (1 paper, 2007). "Majority of genes encoding proteins with enzyme activity or implicated in metabolism were also upregulated in ductal carcinomas (STK4, SLC1A2, B3GALT3, OSBPL10, CRBN, CHML, YWHAB)." (PMID 17389037, 2007).
nodular goiter (1 paper, 2011). Goiter characterized by discrete tissue mass(es) that may or may not produce thyroid hormones. "Among of them, there was a significantly distinct methylation profiling of ABCB4, CYP1B1 and CYP24A1 and SLC1A2 between nodular goiter and normal thyroid tissues (P < 0.05)." (PMID 21988780, 2011).
retina degeneration (1 paper, 2014). "SNTB2 is necessary for eye development in Drosophila, SLC1A2 is a glutamate transporter and glutamate reduction was observed in Müller cell in rd1 retina, and CDK6 is involved in retina degeneration in mice." (PMID 24581223, 2014).
neurological disorders (37 papers, 2011 to 2025). "SFN is located at the center of an interaction network of proteins including HYAL2, NBEA, NBR1, AURKAIP1, RALGPS2, and SLC1A2, some of which have known involvement in brain function and neurological disease." (PMID 31029150, 2019). "The SLC1 subfamily, specifically SLC1A3 (EAAT1), SLC1A2 (EAAT2), and SLC1A1 (EAAT3), are excitatory amino acid transporters that regulate glutamate concentrations in the synaptic cleft, making them important targets for neurological disorder therapeutics." (PMID 40308755, 2025).
neurodegenerative disease (34 papers, 2010 to 2025). A disorder of the central nervous system characterized by gradual and progressive loss of neural tissue and neurologic function. "The dysfunction of SLC1A2 (commonly observed in neurodegenerative diseases) causes elevated levels of glutamate, which yield neuronal damage." (PMID 30957015, 2019). "Dysfunction or reduced expression of SLC1A2 has been linked to neurodegenerative diseases." (PMID 32762776, 2020).
tumor (26 papers, 2015 to 2025). "Moreover, SLC6A14, SLC34A2, and SLC1A2 were linked to tumor immune responsiveness." (PMID 37397501, 2023). "In contrast, the decrease in the AUC for SLC1A2 (0.638–0.586) suggests that its predictive capacity may be confounded by tumor heterogeneity or therapeutic interventions, necessitating dynamic monitoring." (PMID 41431005, 2025).
infection (19 papers, 2012 to 2025). The state of being infected such as from the introduction of a foreign agent such as serum, vaccine, antigenic substance or organism. "Astrocyte Clusters 2 and 5, which made up the majority of naive astrocytes but were largely lost following infection, were enriched for NF‐κB target gene cathepsin S (Ctss) and Glt‐1 encoding gene, Slc1a2, respectively." (PMID 40635167, 2025). "Vascular cells shared six down-regulated DEGs in response to either Aβ pathology or MA10 infection, (Rgs5, Slc1a2, Flt1, Sparcl1, Bsg, Pecam1)." (PMID 41497643, 2025). "Enrichment of populations of astrocytes that upregulate inflammatory‐responsive genes such as Pvalb and Slc16a3 was observed, while astrocyte populations enriched for homeostatic glutamate transporter genes, such as Slc1a2 and Slc1a3, decreased over the course of infection." (PMID 40635167, 2025). "Expression of Slc1a2 was also significantly downregulated in Clusters 1 and 8 relative to naïve uninfected mice, even though these populations expanded after infection." (PMID 40635167, 2025). "In addition, based on fluctuations in cluster populations over the course of infection, Lcn2CreERT2+ RAs seem capable of regaining lost astrocyte housekeeping roles, such as the re‐emergence of Slc1a2 expressing RAs to possibly recover glutamate transport function." (PMID 40635167, 2025).